SMARCB1 (SWI/SNF related BAF chromatin remodeling complex subunit B1)
Diseases named in the same sentence as SMARCB1 in open-access papers (continued):
Sharing a sentence is not in itself a finding about the gene and the disease.
cancer (continued). "Furthermore, he is the third reported case of r22 and 22q13 deletion not including SMARCB1 associated to this rare malignant tumor." (PMID 34777208, 2021). "(a) Volcano plot identifying genes that are required for survival in SMARCB1 deficient cancers." (PMID 30860482, 2019). "Nevertheless, these studies still support the importance of testing this hypothesis in patients, particularly since there are no standard therapies for SMARCB1-deficient cancers." (PMID 30860482, 2019). "However, SMARCB1- deficient carcinoma of the thoracic cavity including lung and pleura has not been reported." (PMID 29625594, 2018). "Alternatively, differences between putative RT subgroups may be too subtle, and not as relevant as differences evidenced between various SMARCB1-deficient cancers, for which our differential analyses were designed." (PMID 28427232, 2017). "Therefore, targeting PHF6 may offer new therapeutic opportunities for SMARCB1-mutant cancers." (PMID 40115023, 2025). "SMARCB1 is a constituent gene of SWI/SNF, although other constituent genes in various cancers also harbor genetic abnormalities." (PMID 39625239, 2025). "Constituent genes (e.g., SMARCB1, SMARCA4, SMARCA2, and SS18) of the SWI/SNF complex often harbor genetic abnormalities in various cancers." (PMID 39625239, 2025). "The aberrations of SMARCB1, SMARCA4, ARID1A, PBRM1, and SS18 within the SWI/SNF complex are frequently found in rare cancers and refractory cancers." (PMID 39625239, 2025). "Confirmation of the role of SMARCB1 as a tumour suppressor gene (TSG) arose when conditional gene knockout in adult mice resulted in CD8+ mature lymphoma and fully penetrant cancer formation." (PMID 40422882, 2025). "The IC50 (50% inhibitory concentration) values derived from JMU-RTK-2 -SMARCB1 cells treated with CBP/p300-specific inhibitors CP-C27, A-485, and inobrodib were markedly lower than those from JMU-RTK-2 +SMARCB1 cells and HEK293T non-cancer cells." (PMID 38839769, 2024). "The re-expression of SMARCB1 has been shown to arrest MRT cells in the G0/G1 phase; however, DNA damage has been shown to activate the G2/M checkpoint in cancer cells, which aligns with our findings." (PMID 38893160, 2024). "A wide variety of benign and malignant tumors with alterations in several genes belonging to the SWI/SNF complex have been described, including SMARCB1, SMARCA4, SMARCA2, and ARID1A." (PMID 39590317, 2024). "Although it was not possible to assess prognosis in one patient, SMARCB1 may also predict immune checkpoint blockade responsiveness independently, which supports the notion that SMARCB1 deficiency may represent a primary event rather than a secondary phenomenon in MSI-associated carcinoma." (PMID 38217014, 2024). "There is an antagonistic relationship between EZH2 and SMARCB1 (as well as other subunits of the SWI/SNFc), resulting in genetic dependence on EZH2 in some SWI/SNF-mutant cancers." (PMID 37446319, 2023). "The mutational rates and variation types of six SWI/SNF complex genes (ARID1A, ARID1B, ARID2, SMARCA4, SMARCB1, and PBRM1) were analyzed retrospectively by integrating next-generation sequencing data of 4591 cases covering 18 cancer types." (PMID 36371186, 2022). "Among newly identified genes, eleven other cancer targets were detected: MPL; ERBB4; VHL; FGFR3; KIT; KDR; PTEN; KRAS; PTPN11; ERBB2; and SMARCB1." (PMID 35621644, 2022). "Considering the origin of ARPE19 and IMR90, regulation of the immune response by SMARCB1 may be relevant and better observed than in other cells of other origins, but we believe that this phenomenon can be expanded in other contexts, especially SMARCB1-dysregulated cells, such as those in cancers." (PMID 32492816, 2020). "Our findings are in agreement with a recent publication identifying the SWI/SNF subunit member SMARCB1 as required to target the SWI/SNF to specific enhancer regions and provide new insights into BRD proteins to a cancer-related SWI/SNF function." (PMID 31000698, 2019).
cancer (continued). "We then assessed what genes were differentially expressed upon SMARCB1 re-expression in the RMC and MRT cell lines as another way to assess the similarity between these two cancers." (PMID 30860482, 2019). "The SMARCB1 immunohistochemical analysis is a very sensitive tool for diagnosing MRT and some carcinomas with rhabdoid features." (PMID 30649642, 2019). "This C>T substitution which results in a truncated SMARCB1 protein is not reported in the general human population (dbSNP v137) but is the second most common SMARCB1 mutation reported in the catalogue of somatic mutations in cancer, Cosmic database (June 2013)." (PMID 26998479, 2015). "Therefore, to consider the impact of differences in proliferation of these cell lines on the results of siRNA screening, we also examined SMARCB1-proficient HEK293T immortalized cell lines and five SMARCB1-proficient cancer cell lines." (PMID 38839769, 2024). "Cancer cells lacking SMARCB1 or SMARCE1 demonstrate heightened ncBAF activity, leading to the induction of a growth-promoting gene expression signature." (PMID 38390898, 2024). "Some adult cancers also show hSNF5 (SMARCB1) abnormalities, although the data for MRT is not included in the analysis." (PMID 37317642, 2023). "Further, there is frequently reactivity with CK5/6, p63, and p40 in SMARCB1-deficient carcinoma, while these markers are generally negative in SMARCA4-deficient carcinomas." (PMID 36941503, 2023). "A case of homozyogously deleted ES occurring in the setting of SMARCB1 constitutional deletion was reported by Le Loarer and coworkers in a 25-year-old ES patient without prior familial or personal history of cancer." (PMID 36078034, 2022). "There is no possibility of preventing cancer development in patients with RTPS, but in case of detected SMARCB1/SMARCA4 mutations, the advice of surveillance and follow-up must be followed." (PMID 33692948, 2021). "Regardless of the fact that little is known about the penetrance of non-rhabdoid SMARCB1-deficient tumors in RTPS, it has been generally accepted that any rare cancer in childhood justifies discussion and referral to genetic testing." (PMID 33532948, 2021). "However, this may not be specific to RT among SMARCB1 deficient cancers." (PMID 28427232, 2017). "Chromosomal microarray analysis (CMA) (Cytoscan HD, Thermo Fisher Scientific) revealed monoallelic loss of SMARCB1, and an NGS panel (Oncomine Childhood Cancer Research Assay; Thermo Fisher Scientific) did not identify pathogenic variants in SMARCB1 or SMARCA4." (PMID 41180011, 2025). "Interestingly, unlike ARID1A, and in contrast to its effect in our screen, SMARCB1 is a prototypical pan-cancer essential gene." (PMID 37554444, 2023). "Additionally, based on the preclinical evidence that supports the presence of an immunogenic microenvironment in SMARCB1-defective tumors, a dedicated phase II clinical trial evaluating the efficacy of nivolumab and ipilimumab SMARCB1-negative pediatric cancers has been launched (NCT04416568)." (PMID 35327458, 2022). "Germline testing results were available in only four patients and detected a pathogenic alteration in SMARCB1 in one patient with unclassified RCC and negative family history of cancer, and a variant of unknown significance in one patient with clear cell RCC (ccRCC)." (PMID 33194712, 2020). "Recent data have shown that the gene DDB1-CUL4-associated factor 5 (DCAF5) is required for the survival of SMARCB1-mutant cancers and actually promotes the degradation of incompletely assembled SWI/SNF complexes in the absence of SMARCB1." (PMID 39125735, 2024).
cancer (continued). "Wider use of gene panels including SMARCB1 and SMARCA4 among many other genes may reveal more carriers of a PV with no cancer phenotype." (PMID 33532948, 2021). "In addition to these five TFs, we identified BATF, SMARCB1, TAF1 and MXI1 as novel TERT regulators across cancer entities that to our knowledge, so far, have not been described in the literature as TERT regulators." (PMID 31888467, 2019). "However, related genes (e.g., CDK1, CDK2, SMARCB1, SMARCA4) were excluded from the present study because they are either well-known genes in cancer or did not have significantly altered messenger RNA (mRNA) levels." (PMID 29712898, 2018). "In addition, several of these genes have not previously been reported as methylated in any type of cancer (KCNK4, SEPT5, PENK, BMP4, TAL1, PGF, SMARCB1 (INI1), FRZB (SFRP3), IRAK3 and MCM2)." (PMID 19493342, 2009).
CNS tumors (19 papers, 2004 to 2025). "Only a subset of pediatric CNS tumors will harbor canonical driver mutations (e.g. in Histone 3, BRAF, NTRK, SMARCB1) and the catalog of prognostic molecular findings is constantly evolving." (PMID 39834946, 2024). "Overall, primary adult sellar SMARCB1/INI1-deficient tumors should be considered a subtype of ATRT, but not PES on the basis of epigenetic analysis, which is a powerful approach for CNS tumor classification." (PMID 35804041, 2022). "Using the DKFZ/Heidelberg CNS Tumour Classifier25 (v11b4), the methylation subtype of the adult sellar SMARCB1/INI1-deficient tumors in our cohort was also determined." (PMID 35804041, 2022). "According to the 2016 WHO Classification of Tumors of the CNS, AT/RT is defined as having specific genetic alterations in the INI1/SMARCB1/hSNF5, or rarely, in the SMARCA4/BRG1 genes." (PMID 33384656, 2020).
infection (12 papers, 2006 to 2025). The state of being infected such as from the introduction of a foreign agent such as serum, vaccine, antigenic substance or organism. "We introduced the SMARCB1 mutant library into the three SMARCB1-deficient cell lines at a low multiplicity of infection (0.2–0.5)." (PMID 40196006, 2025). "In this work we characterized the intracellular localization of SMARCB1 throughout infection showing re-localization to the replication foci." (PMID 22479537, 2012). "However, previous results have shown that UL114 localizes to viral replication foci as early as 5 hpi and co-localizes with UL44 throughout the infection cycle (5–72 hpi), thus indirectly indicating that SMARCB1 and UL114 co-localize." (PMID 22479537, 2012). "We therefore examined the sub-nuclear localization of SMARCB1, UL114 and UL44 in mock and HCMV-infected fibroblasts at early (24 hpi) and late times of infection by biochemical fractionation and western blot analysis." (PMID 22479537, 2012). "We first, analyzed the expression of SMARCB1, UL114 and UL44 in nuclear protein extracts at immediate –early (12 hpi), early (24 hpi) and late (48 and 72 hpi) times of infection." (PMID 22479537, 2012). "We showed that SMARCB1 was recruited to viral replication foci in HCMV-infected cells and co-localized with UL44 throughout the infection cycle (24–72 hpi)." (PMID 22479537, 2012). "Similarly, suppression of SMARCB1 expression enhances autophagy formation and promotes RGDV infection." (PMID 41066408, 2025). "Immunofluorescence microscopy revealed that SMARCB1 along with BRG-1, BAF170 and BAF155, which are the core SWI/SNF components required for efficient chromatin remodeling, were present in virus replication foci 24–48 hours post infection (hpi)." (PMID 22479537, 2012).
neurodevelopmental disorder (8 papers, 2019 to 2026). A behavioral and cognitive disorder with onset during the developmental period that involves impaired or aberrant development of intellectual, motor, or social functions. "Pathogenic variants in genes encoding the BAF complex subunits, including SMARCB1, are responsible for different neurodevelopmental disorders." (PMID 40794298, 2025). "The type and position of the germline PV within SMARCB1 would also appear to play an important role in the context of SMARCB1-associated neurodevelopmental disorders such as CSS." (PMID 40794298, 2025). "Mutations of its core subunit SMARCB1 result in a broad spectrum of pathologies, including aggressive rhabdoid tumours or neurodevelopmental disorders." (PMID 37219662, 2023). "Mutations of SMARCB1 are found in neurodevelopmental disorders as well as in a variety of malignancies." (PMID 37219662, 2023). "As one of its core subunits, Smarcb1 is indispensable for its function and its loss is connected to neurodevelopmental disorders and participates in the carcinogenesis of entities such as rhabdoid tumours." (PMID 35456033, 2022). "Molecular pathogenesis of neurodevelopmental disorders caused by germline SMARCB1 PVs)." (PMID 40794298, 2025). "This study thus confirms the crucial role of SMARCB1 in neuronal development and in the pathogenesis of neurodevelopmental disorders." (PMID 37219662, 2023). "Our results establish a novel role of Smarcb1 in the development of the brain midline and have important clinical implications for BAF complex-related ID/neurodevelopmental disorders." (PMID 31273213, 2019).
adenocarcinoma (7 papers, 2021 to 2024). A common cancer characterized by the presence of malignant glandular cells. "SMARCB1-deficient sinonasal adenocarcinoma is a rare variant of SWI/SNF-deficient malignancies with SMARCB1 loss and adenocarcinoma features." (PMID 38085333, 2024). "Histomorphology of SMARCB1-deficient adenocarcinoma was oncocytoid/rhabdoid and glandular, solid, or trabecular in 9/14 cases." (PMID 38085333, 2024). "These rare cases have been designated as “SMARCB1 (INI-1)-deficient adenocarcinoma”." (PMID 35326613, 2022). "SMARCB1-deficient sinonasal adenocarcinoma is a rare SWI/SNF-deficient malignancy defined by the presence of unequivocal glandular differentiation and/or by the presence of other features of adenocarcinoma." (PMID 38085333, 2024). "This study aimed to investigate the clinical relevance of immunohistochemical expression of proteins of the SWI/SNF complex, SMARCA2, SMARCA4 SMARCB1, ARID1A, ARID1B, and PBRM1 in 477 adenocarcinomas of the stomach and gastroesophageal junction." (PMID 34359794, 2021).
head and neck tumors (4 papers, 2018 to 2025). "In the latest WHO classification of head and neck tumors, NUT midline, SMARCA4-deficient, and SMARCB1-deficient SNCs have been recognized as separate entities." (PMID 36937407, 2023).
genetic disorder (3 papers, 2014 to 2021). "Mutations in Coffin–Siris also occur in SMARCB1 (BAF47), SMARCA4 (BRG1), SMARCE1, ARID1A, and ARID1B, which attests to the role of the SWI/SNF complex in this genetic disorder." (PMID 25774356, 2014). "This genetic disorder is caused by de novo mutations of ARID1A (CSS2; 1p36.11; MIM 614607), ARID1B (CSS1; 6q25.3; MIM 135900), DPF2 (CSS7; 11q13.1; MIM 618027), SMARCA4 (CSS4; 19p13.2; MIM 614609), SMARCB1 (CSS3; 22q11.23; MIM 614608) or SMARCE1 (CSS5; 17q21.2; MIM 616938) genes." (PMID 32916978, 2020).
SMARCB1 also shares sentences with these, for which no sentence is quoted: childhood cancer (16 papers); kidney tumor (10); Epithelioid Malignant Peripheral Nerve Sheath Tumor (8); HIV-1 infection (8); neuroblastoma (7); sinonasal undifferentiated carcinoma (7); small cell carcinoma of the ovary (7); ependymoma (5); gastrointestinal stromal tumor (5); hepatoblastoma (5); tumor predisposition syndromes (5); ovarian clear cell cancer (4); pineal parenchymal tumors (4); Renal neoplasm (4); small cell carcinoma (4); benign tumors (3); epithelioid hemangioendothelioma (3); follicular lymphoma (3); Nicolaides-Baraitser syndrome (3); non-small cell lung carcinoma (3); olfactory neuroblastoma (3); primitive neuroectodermal tumor (3); prostate carcinoma (3); yolk sac tumor (3); adenoma (2); adrenocortical carcinoma (2); angiosarcoma (2); astrocytic tumor (2); Astrocytoma (2); choroid plexus carcinoma (2).
A further 169 diseases each share a sentence with SMARCB1 in 2 papers or fewer.